IL10RA (interleukin 10 receptor subunit alpha)
Diseases named in the same sentence as IL10RA in open-access papers (continued):
Sharing a sentence is not in itself a finding about the gene and the disease.
Obesity (4 papers, 2018 to 2025). Accumulation of substantial excess body fat. "Further genes related to overweight should be investigated, including IL10RA, which is important in inflammatory signaling and many other mechanisms related to overweight or obesity." (PMID 35205336, 2022). "To examine whether early obesity promotes Th2 cytokine signaling in microglia, we quantified IL4Ra and interleukin-10 receptor-alpha (IL10Ra) expression in CD45LO/Ly6CLO/CD169−/TMEM119+ microglia." (PMID 34330904, 2021). "Taking together, these results and the key immunomodulatory role of IL10 suggest that the IL10/IL10RA might act as a brake to limit fat burning and preserve fuel supplies in conditions of acute energy demands as infectious states but also in obesity and aging." (PMID 30158466, 2018). "Additionally, IL10RA mRNA was found to be abundantly expressed in mature adipocytes and upregulated by HFD feeding, obesity, aging and PPARG activation." (PMID 30158466, 2018).
atherosclerosis (3 papers, 2017 to 2024). A disease characterized by the build-up of fatty material and calcium deposition in the arterial wall resulting in partial or complete occlusion of the arterial lumen. "The expression of the genes CYBB, FCER1G, TYROBP, IL10RA, and CSF1R is increased in both ANCA-associated vasculitis and atherosclerosis." (PMID 39702436, 2024). "According to the findings of our research, the genes CYBB, FCER1G, TYROBP, IL10RA, and CSF1R could represent relevant targets for the study and development of therapeutic strategies aimed at ANCA-associated vasculitis and atherosclerosis." (PMID 39702436, 2024).
glioma (3 papers, 2013 to 2024). A benign or malignant brain and spinal cord tumor that arises from glial cells (astrocytes, oligodendrocytes, ependymal cells). "Expression of IL10RA within the leukocyte population (CD45+ cells) was obviously lower in metastases than in both gliomas and meningiomas." (PMID 33490091, 2020).
primary immunodeficiency (3 papers, 2015 to 2020). "Our data suggest that the intestinal microbial profiles may help evaluating and managing the UCBT outcome in pediatric CD patients with IL10RA deficiency and those with primary immunodeficiency and severe malnutrition." (PMID 33162889, 2020).
breast tumors (2 papers, 2009 to 2025). "The top ctSVG for T cells, IL10RA, is highly expressed in the region of cancer in situ in HER2+ breast tumors." (PMID 39979358, 2025).
celiac disease (2 papers, 2010 to 2022). An autoimmune genetic disorder with an unknown pattern of inheritance that primarily affects the digestive tract. "Genetic variants of IL10RA have been shown to inhibit the production of TNF-alpha, a protein known to play a role in coeliac disease." (PMID 20478055, 2010).
head and neck squamous cell carcinoma (2 papers, 2020 to 2024). A squamous cell carcinoma that arises from any of the following anatomic sites: lip and oral cavity, nasal cavity, paranasal sinuses, pharynx, larynx, and salivary glands. "IKZF1 is involved in lymphoid differentiation and its co-expression with SASH3 and IL10RA is associated with good prognosis of head and neck squamous cell carcinoma." (PMID 39107857, 2024).
IPEX syndrome (2 papers, 2017 to 2025). "Hematopoietic stem cell transplantation has been reported as curative for specific monogenic IBD disorders, including CGD, IPEX syndrome, and IL10RA/B deficiencies." (PMID 40426715, 2025).
mastitis (2 papers, 2020 to 2021). Inflammation of breast tissue during lactation or postpartum due to an obstructed duct or infection. "SNPs in the interleukin-10 receptor alpha gene (IL10RA) relate to MAP infection and mastitis in dairy cattle." (PMID 34209174, 2021).
sarcoidosis (2 papers, 2016 to 2020). Sarcoidosis is a multisystemic disorder of unknown cause characterized by the formation of immune granulomas in involved organs. "For example, here, among other genes, STAT1, IL10RA, and PTEN were underexpressed in sarcoidosis CD14 monocytes compared to controls while CXCR4, ATG12, HIF1A, CCR1, and IER3 were overexpressed, consistent with the effects of TGFB1 signaling." (PMID 33363531, 2020).
schizophrenia (2 papers, 2012 to 2017). A major psychotic disorder characterized by abnormalities in the perception or expression of reality. "In addition, the schizophrenia-related genes IL10RA and MMP2 showed a trend towards a reduction, to 33% and 45%, respectively, in medial rectus muscles in this data set." (PMID 29302405, 2017). "Besides categories related to hematological function, the Tan schizophrenia module was also enriched for the Neurological Disease category (CCL5, PRKCQ, PTAFR, AKR1B1, CD247, IL10RA and KHSRP)." (PMID 22761806, 2012).
anaplastic large cell lymphoma (1 paper, 2020). Anaplastic large cell lymphoma (ALCL) is a rare and aggressive peripheral T-cell non-Hodgkin lymphoma, belonging to the group of CD30-positive lymphoproliferative disorders, which affects lymph nodes and extranodal sites. "IL-10RA upregulation drives the resistance to crizotinib in anaplastic large cell lymphoma (ALCL) through an autocrine positive feedback loop." (PMID 32872659, 2020).
Chlamydia infection (1 paper, 2017). "RNA-Seq analysis on the dysregulated genes in macrophages after Chlamydia infection, indicated a threefold upregulation of interleukin-10 receptor subunit alpha (IL-10RA) during C. trachomatis infection of iPSdMs." (PMID 28440293, 2017).
chlamydial infection (1 paper, 2017). "Using CRISPR/Cas9 technology, we generated biallelic knockout mutations in host genes encoding IRF5 and IL-10RA in iPSCs, and confirmed their roles in limiting chlamydial infection in macrophages." (PMID 28440293, 2017).
cognitive decline (1 paper, 2022). "Our data indicate that miR‐15a/16‐1 regulates vascular brain damage and cognitive decline in VCID brains via translational inhibition of its downstream target gene, IL‐10RA." (PMID 35403823, 2022).
diabetic nephropathy (1 paper, 2023). "Our study explored the same platform GEO dataset for diabetic nephropathy bioinformatics analysis and identified eight potential key genes (TYROBP, ITGB2, CD53, IL10RA, LAPTM5, CD48, C1QA, and IRF8), screened eight transcription factors, and identified 93 miRNA nodes." (PMID 37113991, 2023).
Giardia infections (1 paper, 2022). "Several cytokine receptors are differentially expressed during the Giardia infections, including IL11RA, IFNGR1, IFNGR2, IL10RA, and ACKR3." (PMID 35573800, 2022).
glomerulopathy (1 paper, 2022). "The effect of IL10RA upregulation on macrophages in glomerulopathy has not been well illustrated." (PMID 35601837, 2022).
Hashimoto thyroiditis (1 paper, 2023). An autoimmune disorder caused by the production of autoantibodies against thyroid tissue. "The IL10RA, IL10RB, and IL22RA polymorphisms/haplotypes could be associated with SLE susceptibility and various clinical manifestations, and the IL22RA CC haplotype could be associated with Hashimoto thyroiditis." (PMID 37511050, 2023).
Hyperglycemia (1 paper, 2022). An increased concentration of glucose in the blood. "Hyperglycemia easily triggers an inflammatory response, which indirectly promotes the expression of IL10RA and aggravates DN." (PMID 35909518, 2022).
injury (1 paper, 2024). Damage inflicted on the body as the direct or indirect result of an external force, with or without disruption of structural continuity. "Interestingly, Il10ra and Tnf were co‐expressed in M1 macrophages, indicating that IL‐10 could interact with M1 macrophages to trigger M1 transformation during liver injury." (PMID 39352304, 2024).
Insulin resistance (1 paper, 2015). Increased resistance towards insulin, that is, diminished effectiveness of insulin in reducing blood glucose levels. "In contrast, four genes such as IL10RA, TLR3, FOS, and PRL demonstrate strong inverse correlations with insulin resistance." (PMID 26089598, 2015).
lupus nephritis (1 paper, 2021). Glomerulonephritis in the context of systemic lupus erythematosus. "Further analysis revealed that HLA-DPA1, IL10RA, and IRF8 were differentially expressed in different pathological staging samples of lupus nephritis." (PMID 34692653, 2021).
metastatic melanoma (1 paper, 2020). A melanoma that has spread from its primary site to another anatomic site. "Overall, these genes play an important role in tumorigenesis, and we further conducted in vitro experiments to verify that the role of IL10RA gene in the prognosis of metastatic melanoma." (PMID 33490091, 2020). "GSEA was conducted to explore further potential biological functions of IL10RA in metastatic melanoma." (PMID 33490091, 2020). "Furthermore, gene set enrichment analysis revealed that PI3K-AKT signaling pathway is significantly enriched in metastatic melanoma with highly expressed IL10RA, indicating its significance as potential biomarkers." (PMID 33490091, 2020). "Furthermore, gene set enrichment analysis shows that PI3K-AKT signaling pathway is significantly enriched in metastatic melanoma with highly expressed IL10RA, indicating that IL10RA mediates in metastatic melanoma via PI3K-AKT pathway." (PMID 33490091, 2020).
myeloid leukemia (1 paper, 2021). A clonal proliferation of myeloid cells and their precursors in the bone marrow, peripheral blood, and spleen. "The MFI of IL-10RA ranged from 1702 to 3372 and that of IL-10RB from 3977 to 13126 in five myeloid leukemia cell lines (MV4-11, Kasumi-1, U937, Thp-1 and Molm-13)." (PMID 34392305, 2021).
pancreatic cancer (1 paper, 2025). "Therefore, curcumin may play a critical role in development and occurrence of pancreatic cancer by regulating chronic inflammation in tumor microenvironment through modulation of IL10RA signaling." (PMID 40535567, 2025).
pancreatic ductal adenocarcinoma (1 paper, 2025). An infiltrating adenocarcinoma that arises from the epithelial cells of the pancreas. "Our results validate improved IL-10RA and IDO expression in human pancreatic ductal adenocarcinoma (PDAC) tumours (, b), and reveal their robust correlation." (PMID 39592739, 2025).
prostate carcinoma (1 paper, 2013). A carcinoma that arises from epithelial cells of the prostate gland. "Among U.S. men, two inflammatory-related sequence variants, [IL1R2 rs11886877 (GA, GA + AA, AA) and IL10RA rs4252243 AA], were associated with a 1.82-2.49-fold increase in prostate cancer risk." (PMID 24359571, 2013). "Similar to the total population, inheritance of sequence variants in IL1R2, IL10RA and TNF among U.S. men were linked with a significant increase in prostate cancer risk." (PMID 24359571, 2013).
prostatitis (1 paper, 2025). An infectious or non-infectious inflammatory process affecting the prostate gland. "Finally, we obtained 9 SNPs to serve as instrumental variables for evaluating the causal relationship between the IL-10RA cytokine and prostatitis." (PMID 40355178, 2025). "Interleukin-10 receptor A (IL-10RA), Natural Killer Cell Receptor 2B4 (CD244), and urokinase-type plasminogen activator (uPA) may contribute to the occurrence of prostatitis, while Interleukin-12B (IL-12B) appears to serve as a protective factor against it." (PMID 40355178, 2025).
sickle cell disease (1 paper, 2023). Sickle cell anemias are chronic hemolytic diseases that may induce three types of acute accidents: severe anemia, severe bacterial infections, and ischemic vasoocclusive accidents (VOA) caused by sickle-shaped red blood cells obstructing small blood vessels and capillaries. "This means comparably higher numbers of patients with Sickle cell disease reach reproductive age compared to biallelic IL10RA signaling defects that cause untreated neonatal or infantile mortality." (PMID 36370291, 2023).
tumor (97 papers, 2003 to 2025). "In line with our circulating biomarker data, we found that a high level of IL10RA or JAK1 gene expression in tumor tissue was significantly associated with shorter survival after LR in the HCC patients from the TCGA dataset." (PMID 32443546, 2020). "This advances IL-10RA interference in the tumour microenvironment (TME) to restore T cell cytotoxicity against cancers." (PMID 39592739, 2025). "siRNA against TGF-b decreased Treg level and enhanced DC-based cancer vaccine in mice with “cold” melanoma tumor, and siRNA targeting Interleukin-10 receptor alpha (IL-10Ra) initiated tumor-specific CD8+ T cell immune responses." (PMID 36003395, 2022). "Consistent with IL22RA1, higher expression of IL10RB, IL10RA and IL20RB in tumor tissues was associated with worse survival in patients." (PMID 35874683, 2022). "A screen of tumors from ALK+ ALCL patients who progressed within 3 months of crizotinib treatment found that IL-10RA was overexpressed in tumor cells, leading to ALK TKI resistance." (PMID 35211406, 2022). "As a receptor for IL10, IL10RA can regulate tumor immune responses and is highly expressed in HNSCC tissues." (PMID 35480305, 2022). "In fact, previous studies have reported the differential expression of IL10RA in tumors and non-tumor diseases." (PMID 33490091, 2020). "The left panel displays the boxplots of three genes expression profiles including IRF8, CECR1 and IL10RA for tumor and normal samples." (PMID 30210526, 2018). "Our findings suggest that targeting IL10RA expression could offer a novel approach for cancer therapy by reducing IDO levels in the tumour microenvironment (TME), thereby facilitating the reversal of T cells-mediated killing of cancer cells." (PMID 39592739, 2025). "Identification of the specific cellular sources of IL-10 that inhibit tumor immunity and targeted suppression of IL-10 production in those cells, or inhibition of IL-10RA signaling in tumor cells, may offer improved safety and efficacy." (PMID 34489941, 2021). "Our results suggest that mutations that disrupt the interactions of IL-10 with its receptors (IL-10RA and IL-10RB) and α2-macroglobulin (A2M) may enhance inflammation and modulate anti-tumor immunity." (PMID 25056661, 2014). "Thus, the strength of IL-10RA signaling in ALK+ ALCL affects tumor sensitivity to crizotinib." (PMID 35211406, 2022). "Interestingly, this miRNA might post-transcriptionally inhibit two tumor suppressor genes, i.e. IL10RA and AKR1B10 in CRC." (PMID 33968341, 2021). "CD86, IL10RA, TNFSF13B, and CMKLR1 suppress effective anti-tumor immunity while simultaneously potentially promoting pro-tumor immune subsets – representing immunosuppressive signaling." (PMID 41006647, 2025). "It should be noted that the Inflam-TAM 2 geneset, while labelled inflammatory in the source publication, has similarities to the typical immunosuppressive and tumor-promoting TAM phenotype, such as Il10ra." (PMID 41445746, 2025). "The analysis of the gene signature revealed strong positive correlations with multiple immune checkpoints, including HAVCR2, IL10RA, CSF1R, and CD163, suggesting these genes play a role in regulating the immunosuppressive tumor microenvironment." (PMID 40507280, 2025). "C3AR1 expression was positively correlated with chemokines and their receptors in the tumor microenvironment, such as CCR1(R = 0.83), IL10RA (R = 0.92), and INFG (R = 0.74)." (PMID 37005667, 2023). "WGCNA found that 28 genes including CD4 and IL10RA were related to the expression of PTGIS/HRASLS and tumor immune infiltration." (PMID 36703911, 2023). "A total of 30 IL22RA1-correlated genes (e.g. IL17D, IL22RA2, IL20RB, IL10RA, IL10RB, TSLP and TYK2) are involved in the JAK/STAT pathway which promotes tumor progression." (PMID 35874683, 2022).
tumor (continued). "Collectively, it can be proposed that under-expression of both circ_0001666 and circ_0000977, as tumor suppressive circRNAs, contributes to the down-regulation of some tumor suppressive genes in CRC, including RASSF2, IL10RA, and AKR1B10." (PMID 33968341, 2021). "The expression levels of FCGR2B, IL10RA, and HLA-DRA in tumor samples (n=177) were significantly higher (q value < 0.001; log2FoldChange > 1) than in normal pancreatic tissue (n=171; from GTEx database)." (PMID 33845841, 2021). "The C4 subset was annotated as Treg cells based on the high expression signature genes of tumor-infiltrating Tregs (FOXP3, IL2RA, IL2RB, IL2RG, IL10RA, MAGEH1, LAYN, and GATA3)." (PMID 34663810, 2021). "To this end, we first investigated both IL10RA and IL10RB and its downstream targets JAK1 and TYK2 gene expression levels in 370 HCC tumor samples using the publicly available The Cancer Genome Atlas (TCGA) dataset." (PMID 32443546, 2020). "IL-10 and IL-10RA immunostaining indicated that IL-10 was not expressed by tumors; however, IL-10RA expression was highly localized in tumor cells." (PMID 40666494, 2025). "Indeed, the WGCNA of TCGA-LUAD cohort revealed that patients with this tumor phenotype had down-regulated an extensive gene network led by SASH3 and including IKZF1, IL10RA, CD53 and SNX20, all involved in immune activation." (PMID 39107857, 2024). "IL32 was independently and positively associated with Ki67, HIF1A, and ACTA2 and negatively with TJP1 in tumors and with IL10Ra and BCLxL in non-transformed tumor-adjacent tissue." (PMID 33020452, 2020). "Knockdown of IL-10RA in ALCL cell lines resulted in growth arrest, implicating aberrantly expressed IL-10 and IL-22 in autocrine loops that provided a mechanism for aberrant TYK2 activation in tumor cells." (PMID 30131584, 2019). "This suggests that IL-10RA could serve as an alternative target for efficiently modulating immunity through the regulation of IL-10 signalling and IDO expression, particularly relieving the immune-suppressive interaction of tumour cells/stromal cells and cytotoxic T cells with TME." (PMID 39592739, 2025).
infection (70 papers, 2007 to 2025). The state of being infected such as from the introduction of a foreign agent such as serum, vaccine, antigenic substance or organism. "Following electroceutical treatment, anti-infection genes such as Il10ra and Foxp3 were up-regulated, whereas genes promoting immune response and metabolism, including Il17d and Map3k7, were down-regulated." (PMID 39951521, 2025). "This analysis confirmed that during infection there was an upregulation of both Cd79a+Il10+ Bregs (p < 0.02, Mann–Whitney test) and Cx3cr1+Il10ra+ microglia (p < 0.01, Mann–Whitney test)." (PMID 38594373, 2024). "Infection associated receptor encoding genes include CCR1 (encoding a receptor for CCL5), CRLF2 (cytokine receptor like factor 2), IL10RA, TLR2, CD2, CD48 and IL7R." (PMID 35061738, 2022). "Our initial findings were also validated in vMC0-infected BN rats, where infection resulted in the induction of genes associated with macrophage M2 activation (MGL1, ARG1, IL10, and IL10RA) and Th2 genes (IL33 and IL25)." (PMID 30150981, 2018). "Genotypic frequencies and associations of SNPs in IL10, IL10RA/B, TGFB1, and SLC11A1 with MAP-infection status." (PMID 20398313, 2010). "Genes linked to STAT3 during infection were associated with GO terms such as regulation of cell proliferation (CCND1, JUNB), negative regulation of apoptosis (MCL-1, NFKB1), cytokine-mediated signaling pathway (IL10RA, SOCS1), and immune system process (CRK, IRF9)." (PMID 41115066, 2025). "We hypothesized that in this mouse infection model, P. multocida infection led to the up-regulation of a variety of proinflammatory cytokines, which stimulated DC cells to mature and down-regulated IL-10RA to secrete proinflammatory mediators." (PMID 36140754, 2022). "In the same study, infection of moMΦ with Georgia 2007 strain down-regulated other receptors, such as interferon receptors (IFNAR1, IFNAR2, IFNGR) and interleukin receptors (IL4R, IL10RA, IL10RB, and IL17RA), as well as transcriptomic factors (e.g., FOS, JUN, and TBK1)." (PMID 40530033, 2025). "Interestingly, iPSDMs had increased rates of infection with the knockout of IRF5 and IL10RA, indicating that stimulation of these factors might counteract infection." (PMID 32509598, 2020).